ACOT11 (acyl-CoA thioesterase 11)
Description:
Has an acyl-CoA thioesterase activity with a preference for the long chain fatty acyl-CoA thioesters hexadecanoyl-CoA/palmitoyl-CoA and tetradecanoyl-CoA/myristoyl-CoA which are the main substrates in the mitochondrial beta-oxidation pathway.
Synonyms: BFIT; KIAA0707; THEA; STARD14; BFIT1; THEM1
Tractability: Small molecule: a structure with a bound ligand is known. PROTAC: its protein half-life has been measured.
Gene: Protein-coding gene on chromosome 1 (54,542,257 to 54,639,192, forward strand). Ensembl gene ENSG00000162390.
Subcellular location: Mitochondrion matrix; Cytoplasm
Subcellular location (Human Protein Atlas): Cytosol
Pathways (Reactome):
Metabolism: Mitochondrial Fatty Acid Beta-Oxidation
Gene Ontology:
Molecular function: fatty acyl-CoA hydrolase activity; long-chain fatty acyl-CoA hydrolase activity; lipid binding; medium-chain fatty acyl-CoA hydrolase activity; short-chain fatty acyl-CoA hydrolase activity; thiolester hydrolase activity
Biological process: acyl-CoA metabolic process; fatty acid metabolic process; intracellular signal transduction; negative regulation of cold-induced thermogenesis; response to cold; response to temperature stimulus
Cellular component: cytoplasm; cytosol; extracellular exosome; mitochondrial matrix
Genetic constraint (gnomAD): Loss-of-function variants: 68 observed, 76.49 expected, observed/expected ratio (o/e) 0.89, 90% interval 0.73 to 1.09. The upper end of that interval is the gene's LOEUF score, 1.09, which puts it in group 4 of 6, group 1 being the genes least tolerant of losing a copy. Missense variants: 763 observed, 821.61 expected, observed/expected ratio (o/e) 0.93, 90% interval 0.87 to 0.99. Synonymous variants: 279 observed, 318.79 expected, observed/expected ratio (o/e) 0.88, 90% interval 0.79 to 0.97.
Homologues: Orthologues: macaque ACOT11 (97% identical), rabbit ACOT11 (93% identical), dog ACOT11 (93% identical), chimpanzee ACOT11 (92% identical), pig ACOT11 (90% identical), mouse Acot11 (89% identical), guinea pig ACOT11 (89% identical), rat Acot11 (89% identical), tropical clawed frog acot11 (65% identical), zebrafish acot11a (63% identical), zebrafish acot11b (26% identical). Paralogues in human: ACOT12 (45% identical), ACOT7 (13% identical).
Diseases named in the same sentence as ACOT11 in open-access papers:
ACOT11 is named in the same sentence as 20 diseases in open-access papers, as found by Europe PMC text mining. Sharing a sentence is not in itself a finding about the gene and the disease. The quoted sentences say what the papers report.
Obesity (11 papers, 2011 to 2022). Accumulation of substantial excess body fat. "Acot11-deficient mice show resistance to diet-induced obesity and diabetes, however, contrasting, strain-specific effects of this brown adipose tissue-specific enzyme were observed in response to high-fat diet feeding." (PMID 33671116, 2021). "Them1/Acot11 was most highly expressed in brown adipose tissue and the loss of this enzyme in mice results in resistance to high-fat diet induced obesity, fatty liver, and insulin resistance." (PMID 25760036, 2015). "The association of ACOT11 with hyperuricemia might reflect the fact that ACOT11 is implicated in adipose tissue metabolism and that obesity is a risk factor for hyperuricemia." (PMID 28410202, 2017). "A homolog to ACOT11 in mouse has been associated with obesity, but the function of CWF19L2 is unknown." (PMID 22384316, 2011). "ACOT11 (also known as BFIT and Them1) knockout in mice was recently shown to promote resistance to diet-induced obesity despite greater food consumption." (PMID 29362370, 2018). "Acot11-knockout mice show increased energy expenditure and are resistant to diet-induced obesity and its metabolic consequences." (PMID 30091978, 2018). "Acot11, the Cyp4a gene family, FFA levels, and sleep restriction have all been linked to obesity and insulin resistance." (PMID 30091978, 2018). "ACOT11 functions to reduce energy consumption and conserve calories, also suggestive of a role in obesity." (PMID 28410202, 2017). "A DMR was also identified in the gene body of ACOT11 (Chr1: 55088744–55089810) which is enriched in brown adipose tissue and ACOT11 knock-out mice are resistant to diet-induced obesity and show increased energy expenditure." (PMID 25651499, 2015). "The loss of Acot7, Acot11/Them1, Acot13/Them2, and Acot15/Them5 result in phenotypes ranging from increased neurodegeneration to altered susceptibility to high-fat diet induced obesity, fatty liver, and insulin resistance through unknown mechanisms that unexpectedly altered whole body metabolism." (PMID 25760036, 2015). "ACOT11 mRNA levels were increased in mouse brown adipose tissue by cold exposure and decreased by warm temperatures as well as were higher in this tissue of obesity-resistant mice than in obesity-prone mice." (PMID 28410202, 2017). "Acat2 and Scp2 are involved in lipid metabolism while Acot11 is involved in obesity." (PMID 27699085, 2016). "Knockdown of ACOT11 could successfully combat HFD-induced obesity and hepatic steatosis." (PMID 36558373, 2022).
lung adenocarcinoma (4 papers, 2021 to 2025). A carcinoma that arises from the lung and is characterized by the presence of malignant glandular epithelial cells. "Acyl-CoA Thioesterase 11 (ACOT11) is a protein-coding gene, and its high expression in patients with lung adenocarcinoma was associated with cell proliferation and poor prognosis." (PMID 34249950, 2021). "ACOT11 is highly expressed in lung adenocarcinoma cells, promoting proliferation, migration, and invasion, suggesting its role in cancer progression." (PMID 40978035, 2025).
Insulin resistance (3 papers, 2015 to 2022). Increased resistance towards insulin, that is, diminished effectiveness of insulin in reducing blood glucose levels. "ND-fed ERRα3SA mice also showed dysregulated genes encoding proteins involved in hepatic lipid metabolism such as Acot11 and Angptl8, which have been shown to be closely associated with insulin resistance and NAFLD34,35." (PMID 35440636, 2022).
clear cell renal cell carcinoma (2 papers, 2023). "In clear cell renal cell carcinoma (ccRCC), the majority of ACOT members, including ACOT1, ACOT2, ACOT3, ACOT8 and ACOT11, are downregulated in the cancer samples." (PMID 37003979, 2023).
gastric cancer (1 paper, 2025). A primary or metastatic malignant neoplasm involving the stomach. "Compared to untreated controls, salidroside-treated gastric cancer cells showed decreased ACOT11 mRNA/protein expression but increased miR-1343-3p levels." (PMID 40978035, 2025). "We demonstrate that salidroside exerts anti-proliferative effects in gastric cancer by targeting the miR-1343-3p/ACOT11/FFA lipid metabolism signaling pathway, disrupting cancer cell energy production." (PMID 40978035, 2025).
hyperuricemia (1 paper, 2017). An abnormally high level of uric acid. "We have now shown that rs115445569 [C/T (R64Q)] of ACOT11 was related to hyperuricemia, with the minor T allele representing a risk factor this condition." (PMID 28410202, 2017). "We also identified rs188780113 [G/A (R478C)] of ATG2A as a novel determinant of the serum concentration of uric acid as well as rs115445569 of ACOT11, rs116911833 of TRIM7, and rs60854092 of NOTCH2 as potential novel susceptibility loci for hyperuricemia." (PMID 28410202, 2017). "The remaining four genes (ATG2A, ACOT11, TRIM7, and NOTCH2) may be novel loci that influence the serum concentration of uric acid or confer susceptibility to hyperuricemia." (PMID 28410202, 2017). "Three SNPs (rs115445569 of ACOT11, rs116911833 of TRIM7, rs60854092 of NOTCH2) were related (P < 0.05 in at least one genetic model) to hyperuricemia, although there was no SNP significantly [P < 3.57 × 10−4 (0.05/140)] associated with this condition." (PMID 28410202, 2017). "In addition, rs115445569 [C/T (R64Q)] of ACOT11, rs116911833 [G/A (T80M)] of TRIM7, and rs60854092 [T/A (F1689I) of NOTCH2 were related to hyperuricemia, although the genotypes of these SNPs were not related to the serum concentration of uric acid." (PMID 28410202, 2017).
lung carcinoma (1 paper, 2023). "On the contrary, the role of ACOT11 in lung cancer is different from its role in ccRCC." (PMID 37003979, 2023). "Knockdown of ACOT11 alleviates the proliferation, migration and tumorigenesis of lung cancer cells." (PMID 37003979, 2023).
Stroke (1 paper, 2016). Sudden impairment of blood flow to a part of the brain due to occlusion or rupture of an artery to the brain. "Grb2, Acot11, Acat2, Scp2, Anp32b and Ppp2r5d were down-regulated after stroke." (PMID 27699085, 2016).
cancer (4 papers, 2011 to 2025). A tumor composed of atypical neoplastic, often pleomorphic cells that invade other tissues. "Current research on ACOT11 in tumor metabolism remains limited, with only a few other ACOT family members reported to participate in cancer metabolic reprogramming." (PMID 40978035, 2025).
tumor (3 papers, 2020 to 2025). "In particular, ACOT11 was decreased in almost every matched normal-tumor pair, and had extremely high diagnostic value as shown by ROC curve analysis (AUC = 0.964)." (PMID 33362855, 2020). "The in vivo experimental results indicate that salidroside regulates ACOT11 through miR-1343-3p to inhibit lipid metabolism and proliferation in tumour tissues." (PMID 40978035, 2025). "This study establishes a novel anti-tumor mechanism of salidroside in GC through the miR-1343-3p/ACOT11/FFA metabolic axis." (PMID 40978035, 2025). "In vivo studies confirmed that salidroside and miR-1343-3p agomir reduced tumor size, volume, and weight, upregulated miR-1343-3p expression, downregulated ACOT11 at the gene and protein levels, increased fatty acyl-CoA concentration, and decreased acetyl-CoA, FFA, and ATP concentrations." (PMID 40978035, 2025). "This suggests that ACOT11 may be regulated by miR-1343-3p, thereby affecting lipid metabolism and tumor progression." (PMID 40978035, 2025). "The results showed that ACOT1/2/8/11/13 were significantly downregulated in ccRCC tissues compared to that in adjacent non-tumor kidney tissues in all of these datasets, and in particular, the levels of ACOT11 were markedly reduced in almost every matched normal-tumor pair." (PMID 33362855, 2020).
ACOT11 also shares sentences with these, for which no sentence is quoted: breast carcinoma (2 papers); metabolic disorders (2); Alzheimer disease (1); cardiovascular disease (1); cognitive decline (1); colon cancer (1); diabetes (1); Hepatic steatosis (1); liver (1); non-alcoholic fatty liver disease (1).